HIF1A (hypoxia inducible factor 1 subunit alpha)
Diseases named in the same sentence as HIF1A in open-access papers (continued):
Sharing a sentence is not in itself a finding about the gene and the disease.
tumor (continued). "Accumulating evidence has revealed that HIF-1α and HIF-2α inhibitors block tumor growth through multiple mechanisms." (PMID 35794625, 2022). "It has been shown that hypoxia-induced factor 1 (HIF-1α) promotes the expansion of the CD133+ glioma stem cells (GSC), which cooperate in the tumor resistance to therapies." (PMID 35682991, 2022). "After i.v. in a rat intracranial glioma model, HA-MnO2 NP exhibited sustained attenuation of tumor hypoxia by down-regulation of VEGF and HIF-1α expression." (PMID 35624636, 2022). "Macrophage-derived IL-1β activates the IL-1β/HIF-1α/COX-2 axis, enhancing tumor cell EMT and promoting tumor invasion and metastasis." (PMID 36071472, 2022). "It is worth noting that a higher expression level of HIF-1α was observed in the MN-CCPCA (S) group than the MN-CCPCA (M) group, indicating that intermittent irradiation is helpful to reduce tumor hypoxia." (PMID 36266306, 2022). "A second methylation target site of SETD7 on HIF-1α protein (K391) also destabilises HIF-1α but can be reversed by the lysine-specific histone demethylase 1A (also known as LSD1) to induce VEGFA transcription and tumour angiogenesis." (PMID 35326563, 2022). "Studies have shown that HIF-1α activation can upregulate the levels of HK1 and HK2 and that it plays an important role in tumor cell proliferation by enhancing glycolysis activity." (PMID 35957825, 2022). "In contrast, hypoxia-induced autophagy attenuates CTL-mediated tumor degradation by activating the Src Kinase, which phosphorylates STAT3 in a HIF-1α dependent manner." (PMID 35211123, 2022). "PDHK2 was preferentially expressed in the invasive area of the tumor, in contrast to PDHK1, finely regulated by HIF1α, and which was more expressed in pseudopalisading cells surrounding necrotic areas." (PMID 35954433, 2022). "HIF1-α directly binds the STIL promoter under hypoxia, consequently potentiating hypoxia-induced tumor metastasis." (PMID 35365182, 2022). "In tumor cells, PMA stimulation under normoxic conditions was shown to induce HIF-1α via mitogen-activated protein kinase pathways." (PMID 35250391, 2022). "On one hand, HIF-1α can alleviate hypoxia by promoting angiogenesis, on the other hand, HIF-1α can also lead to tumor necrosis." (PMID 35387966, 2022). "In the mice model transplanted with solid tumors, HIF-1α deletion resulted in a decreased number of TIL and a heavy tumor burden, verifying the importance of the adaption to hypoxia." (PMID 36618408, 2022). "In the present review, we highlighted the role and regulation of HIF-2α in both physiology and tumor progression, emphasizing the independent and coregulatory dynamics of HIF-2α compared to HIF-1α." (PMID 35267567, 2022). "Further mechanistic studies found that the up-regulation of miRNAs in exosomes, especially miRNA-21, was mediated by HIF-1α and HIF-2α, while closely related to tumor stage and lymph node metastasis in patients with OSCC." (PMID 35812406, 2022). "In all tumor cohorts vs. SES, tumor microenvironment, leukocyte extravasation, hepatic fibrosis signaling pathway, and HIF1α signaling were among the top significantly activated CPs." (PMID 35480116, 2022). "HIF1A (hypoxia-inducible factor 1-alpha) up-regulates CD133 under hypoxia conditions, and promotes tumor growth and tumor-initiating and metastatic activities." (PMID 36077272, 2022). "Hypoxia induces various proteins and lncRNA expression with HIF-1α or HIF-2α and finally promotes tumor progression and chemoresistance." (PMID 35256612, 2022). "HIF1-α, VEGF, Cyclin D1, Wnt1, and β-catenin expression in the tumor was detected by Western blotting." (PMID 35711625, 2022). "Researches have determined HIF-1α to be an inhibitor and HIF-2α a promoter of aggressive tumor behaviors." (PMID 36364144, 2022). "The R132H mutant of tumor-derived IDH1 showed decreased catalytic activity due to impaired isocitrate binding and reduced α-KG levels, leading to elevated HIF-1α protein levels in human glioblastoma cells." (PMID 34050894, 2022).
tumor (continued). "In this sense, macrophages in hypoxic conditions express not only HIF-1α and HIF-2α, but also ATF4; more importantly, ATF4 is capable of inducing the recruitment of M2 macrophages to the tumor in a hemangioma model." (PMID 35565420, 2022). "Inhibiting glycolysis and decreasing HIF-1α in the TME was also shown to increase the generation of memory T-cells and improve anti-tumor functionality." (PMID 36077845, 2022). "HIF-1a positively correlated with the Clark level and Breslow index, while HIF-2a varied with the LDH and tumor stage." (PMID 36294785, 2022). "PC is generally hypoxic due to its avascular morphology, and PC cells express high levels of HIF-1α and MMP-9 for promoting tumor growth, invasion and metastasis in a hypoxic environment." (PMID 35681664, 2022). "SIRT1 is the downstream target of HIF-1α which is one of the major factors to create a hypoxic TME, contributing to tumor development and progression." (PMID 35496046, 2022). "Collectively, these studies demonstrate that succinate is a critical regulator of tumor progression and angiogenesis and shed lights on SDH, HIF1α and SUCNR1 as valid targets to manipulate angiogenesis in cancer." (PMID 36551845, 2022). "Studies have demonstrated that hypoxia and hypoxia-inducible factors (HIFs) 1 and 2 alpha (HIF1A and HIF2A) are involved in tumor immune escape." (PMID 35659268, 2022). "Immunohistochemical-based analyses (HIF-1α, GLUT-1, VEGF, CA-IX...) have shown a connection between hypoxia and outcome of tumor therapy." (PMID 35158767, 2022). "It is possible therefore, HIF1α first acts as an oncogene and tumor initiator but following a switch in HIF expression, it acts as a tumor suppressor, preventing disease progression." (PMID 36040300, 2022). "HIF-1α can transcriptionally activate GAPLINC, which is highly expressed in gastric cancer tissues and promotes tumor migration and invasion behavior." (PMID 36139386, 2022). "Paradoxically, despite a reduction in blood supply and angiogenesis, the anti-VEGF treatment has been shown to increase tumor cell invasion in GBM, potentially due to an enhanced hypoxic microenvironment and a feedback activation of HIF-1a and PI3K." (PMID 36046049, 2022). "Topotecan exerted its antitumor activity through the prominent diminution of the HIF-1α protein amount, angiogenesis, and expression of genes targeted by HIF-1 in the tumor mass, compared to untreated controls." (PMID 36362482, 2022). "Our previous study showed that the primary anti-tumor activity from the DSF-Cu complex included cell cycle, cell proliferation, senescence, ROS, mitochondrial dysfunctions, ROS-induced HIF-1α, and c-Myc expression." (PMID 36012403, 2022). "This positive feedback system demonstrates the capacity of OC cells to utilize the overproduction of NOX4-derived ROS to activate HIF-1α and VEGF and promote angiogenesis and tumor growth." (PMID 35743145, 2022). "Tumor volume and proliferation were inhibited by IDF-11774 to the same extent as HIF1A knock-down in both WT and 5-FU-R groups." (PMID 34998404, 2022). "Tumor tissues expressed significantly higher levels of WT1, HIF-1α, B-FGF, and c-MYC and significantly lower levels of SLC22A18 relative to autologous renal tissue." (PMID 36818371, 2022). "Moreover, EZH2-mediated histone H3 methylation of HIF1α in macrophages leads to the silence of HIF1α expression and reprograms the immune suppressive microenvironment to the facilitative one, which alleviates the tumor burden and prolongs the overall survival of mice implanted with tumor." (PMID 35693795, 2022). "IHC analysis of de novo tumours derived from KRASG12D-transduced human mammary cells showed increased levels of stress-related translational targets of YB-1, including HIF1α, NRF2, G3BP1 and membranous CAIX, compared to matching normal tissue." (PMID 34294889, 2022).
tumor (continued). "Under hypoxic conditions, hypoxia-induced factor-1α (HIF-1α) becomes stabilized and up-regulates a number of EMT-related transcription factors (e.g., TWIST and SNAIL) that promote tumor metastasis." (PMID 35365182, 2022). "Two HIF subunits, HIF-1α and HIF-2α, are particularly important for tumor maintenance and GSC viability." (PMID 35954407, 2022). "The upregulation of HIF-1α and VEGF are positively correlated with NOX4-derived ROS production in OC cells and promotes angiogenesis and tumor growth." (PMID 35743145, 2022). "Meanwhile, tumor-derived succinate also activates SUCNR1 on the membrane of tumor cells to induce cancer cell migration and EMT through the PI3K/HIF-1α pathway." (PMID 36071472, 2022). "It was found that GSC tumor showed strong expression of Ki-67, moderate expression of EGFR and VEGF, and weak expression of MGMT and HIF-1α." (PMID 36591483, 2022). "TGF-β expressed by tumor cells stimulates the mammalian target of rapamycin (mTOR) pathway and induces the CD73 production while maintaining the stability of HIF1-α." (PMID 35836249, 2022). "HIF-1α and HIF-2α, which share 48% identity in their protein sequences, have been shown to contribute to tumor resistance to radiation therapy." (PMID 35328212, 2022). "Our data provide new insights into the tumour‐suppressive role of PB1 and also links with glycolysis, mTOR and HIF1α in ccRCC." (PMID 35672925, 2022). "By constructing the regulon networks in TAMs, we found that hypoxia-related regulons, EPAS1 and HIF1A, were both activated in the TAM-1 cluster, which differs from the hypoxia response in MES1-like and MES2-like tumor cells." (PMID 35669791, 2022). "Compared with the in vitro cell line results, the tumor RPPA results additionally showed that IACS and IACS + STN inhibited the pro-tumorigenic hypoxia protein, HIF1α." (PMID 35193687, 2022). "Our findings showed that the primary anti-tumor activity from the DSF-CuCl2 complex included cell cycle, cell proliferation, senescence, ROS, mitochondrial dysfunctions, ROS-induced HIF-1α, and c-Myc expression." (PMID 36012403, 2022). "Meanwhile APC reduces HIF-1α mRNA in a β-catenin l-dependent manner, implying that HIF-1α downregulates APC further improves tumor cell survival under hypoxia." (PMID 35928881, 2022). "We next performed in situ proximity ligation assay between HIF1α and sXBP1 in human/mouse astrocytes and GBM tumour cells depleted of sXBP1 targets SREBP2/ACSS2." (PMID 34811795, 2022). "Of note, we also found that NOX4 expression positively correlated with HIF1α (resistant marker), Glut1 and LDHA (glycolytic markers), and Ki67; whereas it negatively correlated with Bcl2 in tumor tissues in patients with PTC." (PMID 35396551, 2022). "This study discovers that Par can inhibit the HIF-1α-mediated glycolysis of HCC cells by targeting P50, thereby exerting an anti-tumor effect." (PMID 36260873, 2022). "Knockdown of TMEPAI in TNBC led to robust inhibition of in vivo tumor growth accompanied by reduced VEGF and HIF1α tumor promoters and enhanced levels of PTEN and p27 tumor suppressors." (PMID 35326728, 2022). "In orthotopic tumor models, both OCUM-12 and OCUM-12/Hypo tumors were positive for HIF-1α, exhibiting heterogeneous expression throughout the tumors." (PMID 35681691, 2022). "In fact, treatment of GPx2 KD tumor-bearing mice with echinomycin, a drug that inhibits HIF1α, reduced VEGFA expression and tumor growth, while improving vessel maturation, underscoring the effect of GPx2 loss on vascular malfunction." (PMID 35193955, 2022). "PDAC is characterized by a severely hypoxic microenvironment, and USP25 depletion abrogates HIF-1α transcriptional activity and impairs glycolysis, inducing PDAC cell death in the tumor hypoxic core." (PMID 35440539, 2022).
tumor (continued). "On the other hand, in tumor tissues, incomplete TACE induces ischemic conditions, leading to the upregulation of hypoxia-inducible factor 1-α (HIF-1α)." (PMID 36551623, 2022). "Furthermore, it has been reported that iron transporters, such as SLC25A37 and SLC25A28, may be degraded by PINK1/Parkin‐mediated mitophagy, thus leading to the accumulation of iron in mitochondria, which can trigger a HIF1a‐dependent Warburg effect and inflammasome activation in tumour cells." (PMID 36200262, 2022). "Hypoxia contributes to tumor cell immune escape by inducing cytotoxic T lymphocyte (CTL) apoptosis through increased PD-L1 expression, a process that is dependent on HIF1A signaling." (PMID 35659268, 2022). "Studies have shown that lactate derived from tumor cells can induce the expression of vascular endothelial growth factor (VEGF) and arginase 1 (ARG1) through the HIF1A signaling pathway and promote the polarization of TAM to M2-like." (PMID 35281061, 2022). "Knockdown of MT1X in the setting of hypoxia reduces the accumulation of HIF-1α, EPO, VEGF, and CA9, which are important factors that regulate tumor cell adaptation to hypoxia (P<0.05)." (PMID 36149322, 2022). "An in vivo tumor treatment model of MEL was established by s.c. injecting SMMC-7721 cells into male BALB/c nude mice, which showed the significantly inhibited HIF-1α expression and tumor growth." (PMID 36238572, 2022). "The authors showed a correlation between clinical outcomes and viperin expression levels in multiple cancer tissues and proposed that viperin expression was upregulated in the tumor microenvironment via the JAK/STAT and PI3K/AKT/mTOR/HIF-1α pathways." (PMID 36519538, 2022). "Since the expression of HIF-1α is regulated by mammalian target of rapamycin (mTOR), the amount of 18F-FDG in tumor cells also depends on mTOR signaling." (PMID 36536190, 2022). "HIF‐1α and/or Glut‐1 knockout also abrogated PI3K/Akt/mTOR signalling transduction in tumour tissues, in a manner similar to wortmannin." (PMID 35415942, 2022). "Whereas irradiation enhances MHC class-1 expression, hypoxia and HIF-1α suppress the expression of MHC class-1, limiting the tumor cell recognition by APCs." (PMID 35805044, 2022). "After ATP is released by dying tumor cells during RT-induced ICD, it can be hydrolyzed to ADO by CD39 and CD73 upregulated by hypoxia-induced HIF1-α in TIME." (PMID 35836249, 2022). "HIF1α regulates the secretion of several angiogenic factors, including VEGF (vascular endothelial growth factor), from tumor cells into cancer microenvironment, subsequently promoting angiogenesis." (PMID 35123491, 2022). "In summary, DFO reduced the proliferation and tumor growth, obstructed the cell cycle and ROS production, and induced apoptosis of ALL cell lines by inactivating the HIF-1α/PHD-2, Wnt/β-catenin, and p38MAPK/ERK pathways by iron depletion." (PMID 35237325, 2022). "According to western blotting results, the protein expression levels of HIF‐1α, GSK‐3β, and PKM2 proteins were downregulated, indicating that the microenvironment of tumor hypoxia and abnormal metabolism was improved after administration." (PMID 39188744, 2022). "It has been confirmed by a study that downregulated FDFT1 is related to late tumor progression and worse prognosis in CRC, and FDFT1 suppresses the tumorigenesis through negative regulation of AKT/mTOR/HIF1α signaling pathway." (PMID 36160009, 2022). "As a result, increased HIF1-α upregulates the expression of VEGF, FGF or PDGF and increases tumor angiogenesis." (PMID 36551623, 2022). "It has been found that PBRM1 modulates HIF1a-VEGF signal and STAT3-Interferon signal and BAP1 promotes genomic instability and therefore accelerates tumor metastasis." (PMID 35439951, 2022). "Thus, inhibition of HIF‐1α in tumour‐infiltrating NK cells could be applied for cancer therapy." (PMID 35906816, 2022). "HIF-1α expression is positively regulated by TNF-α, a major inflammatory cytokine that induces necrosis in certain tumor types." (PMID 35372052, 2022).
tumor (continued). "Patients with high HIF-1α expression exhibited low TILs, indicating an immunosuppressive phenotype, whereas HIF-1α inhibition suppressed alleviated tumor immunosuppression." (PMID 36032082, 2022). "Even though the expression of HIF1α and CA9 was the same in these two groups, tumor tissues derived from mice injected with HepG2 cells overexpressing CFHR3 had lower PCNA expression levels." (PMID 35549979, 2022). "To determine the role of METTL4 in tumorigenesis, we tested the role of METTL4 in hypoxia-induced tumor progression since hypoxia/HIF-1α induces the epithelial-mesenchymal transition (EMT) and tumor metastasis." (PMID 36461076, 2022). "Many lncRNAs in cancer cells have been found to be regulated by HIF-1α, leading to altered expression levels, and changes in the levels of some of these lncRNAs can promote the progression of EMT in tumor cells." (PMID 36139386, 2022). "In this study, we noted elevated expressions of TLR4, NF-κBp65, and HIF-1α in EOC specimens, and their expressions were significantly correlated with the histological differentiation degree of the tumor." (PMID 35464826, 2022). "Generally, it is agreed that HIF-1A is involved which modulates the expression of VEGF-A, and angiopoietin-1, thus increasing tumour angiogenesis, glycolysis and cellproliferation." (PMID 36612205, 2022). "Conversely, the ALDH+ epithelial CSC population is localized within the tumor core and is characterized by E-cadherin expression, low EMT-related signal enrichment and increased Wnt, HIF1α, glycolytic and proliferative pathway enrichment." (PMID 35326728, 2022). "Sorafenib can resist tumor by inhibiting the expression of CD31, alphaSMA, pERK, VEGF, PDGF, TNFalpha, eNOS and HIF-1α/SLC7A11, BRAF/MAPK signaling pathways." (PMID 36544713, 2022). "In NSCLC patients, transforming growth factor (TGF-β) induces CD39 and CD73 expression on MDSCs through the mTOR/HIF-1α signaling, which makes CD39+CD73-MDSCs highly enriched in tumor tissue and produces adenosine to inhibit T cell activity." (PMID 36237333, 2022). "While it is true, recent advances have revealed multiple molecular mechanism as a prevalent tumor therapy, such as CD24/Siglec-10, EMT, PD-L1/PD-1, C/EBPβ transcription factors and hypoxia/HIF-1α." (PMID 36685947, 2022). "Hypoxia-inducible factor 1-alpha (HIF-1α) is a transcription factor expressed under hypoxic conditions and can promote angiogenesis by increasing VEGF expression in the tumor tissue." (PMID 36686483, 2022). "It is known that HIF-1α regulates a large group of genes/proteins involved in cell metabolism, pH, and EMT, thus making tumor cells more aggressive than that of other phenotypes." (PMID 35800058, 2022). "We selected hexokinase 2 (HK2), Hypoxia-inducible factor 1-alpha (HIF1A), glycolytic enzymes glucose transporter 1 (GLUT1) as well as GLUT3 that have been fully confirmed to participate in aerobic glycolysis in tumor for further validation." (PMID 34996491, 2022). "Elevated levels of HIF1A, its target CAIX, and VEGFA transcripts are also seen in tumours with a gain of function or amplification of YB-1, although this was not the case for G3BP1 or NFE2L2 (encoding NRF2)." (PMID 34294889, 2022). "While many HDAC4 targets have been identified, they focused on HIF-1α, one of the central players of tumor progression and drug response and VEGFA, one of the best-characterized HIF-1α targets." (PMID 36014432, 2022). "Luminal A tumours have the lowest frequency of HIF-1α positivity, and the frequency of HIF-1α-positivity is then increasing step by step in luminal B, HER2-positive and triple-negative tumours." (PMID 35140341, 2022). "HCC cells can adaptively induce hypoxia-inducible factor 1α (HIF-1α) under hypoxic conditions after TACE, promoting tumor growth and metastasis and worsening prognosis." (PMID 36439456, 2022).